MTAP (methylthioadenosine phosphorylase)
Diseases named in the same sentence as MTAP in open-access papers (continued):
Sharing a sentence is not in itself a finding about the gene and the disease.
melanoma (continued). "Interestingly, methylthioadenosine phosphorylase (MTAP) also resides on chromosome 9p21 and can be epigenetically silenced in melanoma, resulting in impaired STAT1 signaling and serving as a marker of response to IFN-α therapy." (PMID 29050360, 2017). "Notably MTAP is lost in ~25% of melanomas due to its proximity to CDKN2A, a commonly deleted tumour suppressor gene, exposing this as a potentially therapeutically relevant vulnerability in melanoma." (PMID 28097822, 2017). "Tests of genetic association performed on observed allele counts in normal and primary melanoma samples showed a positive, albeit not significant association of MTAP rs7023954*G (OR 1.746, 95% CI = 0.6928–4.4006) with melanoma." (PMID 27479139, 2016). "To date, the non-synonymous SNP rs7023954 in exon 3 of the MTAP gene, which results in a conservative substitution of a branched-chain amino acid residue at position 56 for another, has not been linked to melanoma development." (PMID 27479139, 2016). "In addition, expression of MTAP in an MTAP-deleted melanoma cell line or gastric cancer cell line results in reduced invasion and migration in vitro." (PMID 23840755, 2013). "There is evidence that loss of MTAP results in an inhibition of STAT signalling pathways regulated by interferon, so it is of interest that response of melanoma patients to interferon used as an adjuvant therapy for this cancer has been reported to be related to MTAP status." (PMID 20140953, 2010). "We were able in this study to look at deletion of MTAP in primary melanomas." (PMID 20140953, 2010). "The subtype-specific association of the MTAP locus identifies it as a plausible candidate for the nevus-associated pathway, while the age-dependent effect of IRF4 underscores the heterogeneity of melanoma susceptibility and the complex interplay between genetic and environmental factors." (PMID 41596618, 2026). "In doing so, the melanoma risk locus on chromosome 9 upstream of the MTAP/CDKN2A region reached genome-wide significance (without skin color as a covariate: per-allele odds ratio (OR) = 1.32, P = 3.0 x 10−7; with skin color as a covariate: per-allele OR = 1.42, P = 3.8 x 10−8)." (PMID 28973033, 2017). "However it is biologically plausible that variants affecting the genes MTAP, CDKN2A and ANRIL could have an important role in melanoma etiology." (PMID 23816148, 2013). "In addition, genes not involved in pigmentation were associated with an elevated risk of developing melanoma, including germline mutations in MTAP (methylthioadenosine phosphorylase), an enzyme playing a major role in polyamine metabolism and PLA2G6 encoding a phospholipase A2 group VI." (PMID 24416617, 2013). "To investigate the function of the MTAP-ANRIL fusion gene, we constructed a MTAP-ANRIL fusion gene plasmid and transfected it into melanoma cell lines to establish the A375-MTAP-ANRIL and A875-MTAP-ANRIL stable cell lines." (PMID 37277447, 2023). "In summary, our present study demonstrated that MTAP-ANRIL gene fusion can downregulate the expression of the wild-type tumor suppressor MTAP and promote melanoma cell migration via EMT-like process through the activation of JNK and p38 MAPKs." (PMID 37277447, 2023). "Our results suggest that MTAP-ANRIL is a potential molecular prognostic biomarker and therapeutic target for melanoma." (PMID 37277447, 2023). "This fusion gene, documented to exhibit a frequency exceeding 7% in melanoma, results from a chromosomal rearrangement between ANRIL and MTAP, a tumor suppressor gene involved in purine metabolism (methylthioadenosine phosphorylase)." (PMID 37627188, 2023). "The MTAP-ANRIL fusion gene is the most frequently identified fusion gene in melanoma, with a frequency of greater than 7% across all melanoma cell lines and approximately 20% in melanoma cell lines and tissues with chromosome 9p21 deletion." (PMID 37277447, 2023).
melanoma (continued). "Here, we further observed that MTAP-ANRIL downregulated the expression of the wild-type tumor suppressor gene MTAP and promoted melanoma cell proliferation and metastasis." (PMID 37277447, 2023). "We excluded the following genes that were methylated and deleted in melanoma: PTEN, BRIMS1, FERMT3 (KIND3), AKAP12 (SSeCKS), CDKN2A, APAF-1, MTAP and MEN1." (PMID 34639015, 2021). "Nevertheless, our results in this study show that in melanoma cell lines and primary tumors with focal deletion at the CDKN2A/B locus, the transcription of MTAP-ANRIL fusion gene is a frequent occurrence." (PMID 26909863, 2016). "We also detected fusion transcripts involving MTAP and ANRIL in two of the seven primary melanoma tumors with focal deletion at the locus." (PMID 26909863, 2016). "The transcription of the fusion gene involving MTAP and ANRIL as a more general phenomenon was indicated by detection of such transcripts in 13 of 64 cell lines and in two of the 7 primary melanoma tumors with focal deletion at the locus." (PMID 26909863, 2016). "More studies should be performed to further confirm the functions of MTAP-ANRIL, which could be a molecular prognostic biomarker as well as a therapeutic target for melanoma." (PMID 37277447, 2023). "In many human malignancies, such as leukemia, lymphoma, lung cancer, pancreatic cancer, and melanoma, MTAP is frequently suppressed or absent, making it a potential target for cancer treatment." (PMID 36913304, 2023). "Regarding patient stratification, co-deletion with methylthioadenosine phosphorylase (MTAP) and the tumor suppressor gene CDKN2A (p16) are observed in 40% of glioblastomas, 25% of melanomas and pancreatic adenocarcinomas, and 15% of non-small cell lung carcinomas." (PMID 37342192, 2023). "Interestingly, previous work has suggested that melanomas with low MTAP have decreased cGAS-STING signaling, and MTAP is often co-deleted/silenced with CDKN2A." (PMID 33550279, 2021). "Interestingly, MTAP and CDKN2A are frequently homozygously co-deleted otherwise, inactivated in tumor cells including melanoma, resulting in higher intra and extracellular MTA levels." (PMID 20529342, 2010). "Other than MTAP and SEPTIN5, CDKN2A, CDKN2B, HIRA, and DGCR8 were the only recurrently altered cutaneous melanoma genes that were not recurrently altered in acral or mucosal melanomas, which frequently lack the presence of UV-induced mutations." (PMID 38758740, 2024). "TNG908 demonstrated selectivity and efficacy in about 200 cancer cell lines with MTAP deletion independent of their histology (cancers of bladder, CNS breast, heat and neck, pancreas, lung, gastric, uterine as well as mesothelioma, sarcoma, melanoma, leukemia and lymphoma)." (PMID 41465382, 2025). "By reviewing literature, only one Singaporean case with germline 9p21.3 deletion involving CDKN2A, CDKN2B, and partial MTAP and ANRIL genes had no melanoma but squamous cell carcinoma in the head and neck." (PMID 40046620, 2025). "Overexpression of MTAP-ANRIL increased the phosphorylation of JNK and p38 but not Akt or ERK1/2 in melanoma cells." (PMID 37277447, 2023).
mesothelioma (44 papers, 2009 to 2026). A usually malignant and aggressive neoplasm of the mesothelium which is often associated with exposure to asbestos. "Final histopathology confirmed sarcomatoid mesothelioma with high-grade spindle cell morphology, brisk mitotic activity, necrosis, and MTAP loss." (PMID 42052488, 2026). "In mesothelioma and glioma, for instance, concordant loss of p16 and MTAP has been shown to correlate strongly with CDKN2A/B deletion, outperforming either marker alone." (PMID 41596618, 2026). "Overall, our data question the widespread assumption of MTAP as a universal surrogate for CDKN2A status across all mesothelioma subtypes, underlining the need for site‐specific validation." (PMID 40566743, 2025). "Although CDKN 2A copy number loss and MTAP copy number loss are frequently associated with mesothelioma, either MTAP copy number loss or CDKN 2A copy number loss can be seen in lung adenocarcinoma independently." (PMID 40028792, 2025). "Loss of BAP1 and MTAP can support the diagnosis of mesothelioma versus benign mesothelial proliferation: however, morphology (with an invasive pattern) is still the essential tool to distinguish malignant from benign disease." (PMID 39030439, 2024). "One of the significant aspects noted herein is that both the MIS and invasive mesothelioma exhibited loss of methylthioadenosine phosphorylase (MTAP) and homozygous deletion of cyclin-dependent kinase inhibitor 2A (CDKN2A)." (PMID 38017544, 2023). "Both the mesothelioma in situ and invasive lesion showed immunohistochemical loss of methylthioadenosine phosphorylase (MTAP) and homozygous deletion of cyclin dependent kinase inhibitor 2A (CDKN2A) on fluorescence in situ hybridization." (PMID 38017544, 2023). "Homozygous deletion of MTAP is associated with multiple tumors such as mesothelioma, bladder urothelial carcinoma, pancreatic carcinoma, lung carcinoma, leukemia, and glioma among others." (PMID 36572880, 2022). "MTAP copy number loss was assessed in 79 mesotheliomas acquired at radical surgery involving extended pleurectomy decortication (EPD)." (PMID 33795785, 2021). "MTAP deficiency has been reported for several tumor entities, with high frequency in mesothelioma, T cell acute lymphoblastic leukemia (T-ALL), gliomas, metastatic melanoma, and non-small cell lung cancer (NSCLC)." (PMID 33123121, 2020). "The loss of MTAP has been reported in a variety of solid tumors, including mesothelioma." (PMID 37445594, 2023). "Since the loss of BAP1 and MTAP immunostaining is indicative of a malignant transformation in mesothelial cells and is frequently found in mesothelioma with an epithelioid component, several studies investigated the diagnostic role of these markers, even in its sarcomatous counterpart." (PMID 36673059, 2023). "Furthermore, cases of mesothelioma, even those of an in situ lesion, with MTAP loss and/or CDKN2A deletion should be carefully followed up or subjected to early treatment." (PMID 38017544, 2023). "MTAP loss is a reliable surrogate for CDKN2A (p16) homozygous deletion in mesothelioma diagnosis." (PMID 36237331, 2022). "Besides GBM, MTAP loss is seen in a wide variety of cancers including mesothelioma, bladder urothelial carcinoma, and pancreatic carcinoma among others, and MTAP is also considered as a tumor suppressor gene." (PMID 36572880, 2022). "Almost all of our mesothelioma cases exhibited a loss of MTAP and CDKN2A." (PMID 33304846, 2020). "Loss of either MTAP protein or the MTAP gene is frequent in a large number of different human tumors, including leukemias, lymphomas, mesothelioma, lung carcinoma, pancreatic carcinoma, squamous cell carcinoma, biliary tract cancer, glioblastoma, osteosarcoma, and neuroendocrine tumors." (PMID 25387827, 2014). "By contrast, the evaluation of MTAP IHC expression with a 30% cut‐off, as suggested by the International Mesothelioma Interest Group, seems to increase sensitivity despite markedly lowering specificity." (PMID 40566743, 2025).
mesothelioma (continued). "Immunohistochemical evaluation for the MTAP protein showed complete negativity in two cases of epithelioid (28.6%) and two cases of biphasic (33.3%) mesotheliomas." (PMID 39858033, 2025). "MTAP expression is reduced in several cancers, including leukemia, lymphomas, mesotheliomas, lung, and pancreatic cancers." (PMID 40506895, 2025). "On the other hand, three cases (42.8%) and one case (16.7%) of epithelioid and biphasic mesotheliomas, respectively, showed “strong” cytoplasmic positivity; hence, MTAP expression was considered retained." (PMID 39858033, 2025). "PRMT5 inhibitors exerted promising effects on in vitro models of mesothelioma with MTAP deletion, as its inhibition selectively inhibited tumor cell proliferation and downregulated genes related to cell cycle and epithelial–mesenchymal transition." (PMID 40362535, 2025). "(as IHC for BAP1 and MTAP) can be used to support the diagnosis of mesothelioma versus benign mesothelial proliferation." (PMID 39030439, 2024). "In one mesothelioma with heterozygous CDKN2A-MTAP deletion, positive MTAP expression was seen in 60% of the tumor cells, whereas p16 was completely negative." (PMID 37894345, 2023). "Nine mesotheliomas (17%) showed a heterogeneous p16 and MTAP expression, with labeling of both markers in a proportion of cores or tumor cells ranging from 10 to 90% of cells." (PMID 37894345, 2023). "In situ mesothelioma needs to be diagnosed by immunohistochemical detection of BAP1 and/or MTAP loss, and/or by fluorescence in situ hybridization detection of CDKN2A homozygous deletion, and fully discussed with thoracic surgeons and radiologists in MDT." (PMID 37461124, 2023). "Given the close proximity of the CDKN2A and MTAP genes, loss of MTAP immunoreactivity has been suggested as a surrogate for CDKN2A HD and has been demonstrated in mesothelioma." (PMID 37504251, 2023). "Due to its proximity to CDKN2A, homozygous deletion of MTAP occurs frequently in various tumors, including mesotheliomas." (PMID 37894345, 2023). "Similar to studies in mesotheliomas, we also identified one lymphoepithelial carcinoma with the preserved expression of mTAP despite the homozygous deletion of CDKN2A." (PMID 35565429, 2022). "In mesotheliomas, MTAP has been shown to be frequently co-deleted with CDKN2A; both genes are located close to each other on chromosome 9p21." (PMID 35565429, 2022). "The role of BAP-1 and MTAP in the diagnosis of mesothelioma in situ and in the prognosis of malignant pleural mesothelioma is the main topic of recent studies." (PMID 36553016, 2022). "MTAP loss is more common in sarcomatous mesothelioma; on the other hand, BAP-1 loss is more common in the epithelioid form of mesothelioma." (PMID 36553016, 2022). "Earlier studies showed a homozygous deletion of CDKN2A in 74% of mesothelioma samples and co-deletion of MTAP in 91% of these cases." (PMID 36138075, 2022). "Many recent studies have used MTAP IHC to increase the sensitivity in diagnosing mesothelioma, since previous studies indicated that p16 IHC has poor concordance with homozygous CDKN2A loss in MPM." (PMID 33304846, 2020). "In agreement with previous studies underlining the potential value of PRMT5 as a therapeutic approach, our results represent a starting point for the evaluation of PRMT5 inhibitors also in MTAP‐deleted mesothelioma." (PMID 32301278, 2020). "About 40% of non-small cell lung, pancreatic, and biliary tract cancer, 70% of mesothelioma and glioblastoma, and 35% of osteosarcoma, soft-tissue sarcoma, and T-cell acute lymphoblastic leukemia lack MTAP." (PMID 19478948, 2009). "MTAP gene deletions are frequently observed in various cancers, including mesothelioma." (PMID 40362535, 2025). "Two cases (28.6%) of epithelioid and three cases (50%) of biphasic mesotheliomas, respectively, showed “faint” positivity (i.e., lower than the internal control) and were considered negative (i.e., MTAP loss of expression)." (PMID 39858033, 2025).
mesothelioma (continued). "Recently, there have been studies conducted with mesothelioma, various epithelial tumors, meningioma, and pleomorphic xanthoastrocytoma (PXA) in order to use methylthioadenosine phosphorylase (MTAP) immunohistochemical expression loss as a surrogate biomarker to detect CDKN2A HD status." (PMID 38109891, 2024). "On the other hand, for MTAP deficient mesothelioma, although L-alanosina is not being further investigated, at least one trial is ongoing with a different drug, PRMT5-MTA inhibitor." (PMID 37445594, 2023). "One of these drugs is L-alanosina, which has been evaluated in a phase 2 trial including 65 patients with MTAP-deficient solid tumors (16 mesotheliomas): there were no objective responses, although 24% had stable disease, including 2 patients with mesothelioma." (PMID 37445594, 2023). "Durable tumor regressions were noted in about 30% of the MTAP-deleted xenograft models, including models with bladder cancer, cholangiocarcinoma, NSCLC, glioblastoma, mesothelioma, leukemia and lymphoma." (PMID 41465382, 2025). "Methylthioadenosine phosphorylase (MTAP) is frequently subject to deletion in various types of human cancers, including approximately 50% of GBM, 40% of mesotheliomas, and 13% of NSCLC." (PMID 39885614, 2025). "Several studies have investigated MTAP IHC as a marker of CDKN2A status in various tumor types such as diffuse glioma, pleomorphic xantroastrocytoma, and mesothelioma." (PMID 39409918, 2024). "Additionally, BAP1, enhancer of zeste 2 Polycomb progress complex 2 subunit, and S-methyl-5’-thioadenosine phosphorylase (MTAP) loss detected by immunohistochemistry, or CDKN2A (p16) homozygous deletion by FISH is used for differentiation between benign mesothelial proliferation and mesothelioma." (PMID 39006698, 2024). "In a study of 40 mesotheliomas, homozygous deletion of CDKN2A occurred together with homozygous (n = 5) or heterozygous (n = 5) deletion of MTAP or normal MTAP (n = 3)." (PMID 35565429, 2022). "MT-DADMe-Immucillin A (ImmA), a highly potent transition state inhibitor of MTAP, was used to address the effect of MTAP on pemetrexed activity in two mesothelioma cell lines, NCI-H28 MTAP (+) and NCI-H2052 MTAP (−)." (PMID 31965001, 2020). "Recently, loss of expression of BRCA1 associated protein 1 (BAP1) and/or methylthioadenosine phosphorylase (mTAP) has been described in various carcinomas and mesotheliomas but not in reactive mesothelial proliferation." (PMID 35565429, 2022). "Interestingly, in 55 to 91% of mesotheliomas, CDKN2A deletions have been described in tandem with deletions of MTAP, a gene that is located close to CDKN2A on chromosome 9p21." (PMID 35565429, 2022). "MTAP and CDKN2A are homozygously co-deleted, with a frequency of 35 to 70%, in lung and pancreatic cancer, glioblastoma, osteosarcoma, soft-tissue sarcoma, mesothelioma, and T-cell acute lymphoblastic leukemia." (PMID 19478948, 2009). "Recent studies have indicated that the lack of BAP1 and MTAP expression, along with the homozygous deletion of CDKN2A identified through FISH, can effectively differentiate mesothelioma from benign proliferations." (PMID 40432917, 2025). "Moreover, there was a greater reduction in tumor volume observed in patients with MTAP-negative mesotheliomas compared to those with MTAP-positive mesotheliomas, suggesting that CDKN2A and MTAP codeletions may select for patients who will derive a greater benefit from abemaciclib." (PMID 38610930, 2024). "A number of phase 2 clinical trials attempted to treat MTAP‐low tumors including NSCLC and mesothelioma with continuous infusion of L‐alanosine, but failed to reveal clinically significant results." (PMID 35747993, 2023). "Another two cases, both with a predominant pleural tumor mass (patient 4 and 7), were initially classified as mesothelioma, although all mesothelial markers such as calretinin, WT1, D2-40 and CK5/6 tested negative and BAP-1 and MTAP were retained." (PMID 35864317, 2022).